TLR4 (toll like receptor 4)
Diseases named in the same sentence as TLR4 in open-access papers (continued):
Sharing a sentence is not in itself a finding about the gene and the disease.
colitis (continued). "The anti-colitis mechanism of pinocembrin might be associated with improving the disturbed gut microbiota composition, suppressing TLR4/MD2/NF-κB signaling cascades, and preserving intestinal barrier integrity." (PMID 32687156, 2020). "In fact, the TNBS induced colitis causes an increase in the expression of TLR4, IL-1β, and IL-8." (PMID 32183497, 2020). "Moreover, in colitis-associated tumors, TLR4 has been shown to induce an inflammatory microenvironment." (PMID 32095158, 2020). "Taken together, DSS-induced colitis was accompanied by severe dysbiosis in the mucosa-adherent microbiota, and the concomitant application of HnAb resulted in a shift towards the control group, both in WT and in TLR4-deficient colon." (PMID 33193406, 2020). "Using these criteria DSS colitis is more severe in TLR4 deficient mice than in wild type mice." (PMID 33552081, 2020). "Moreover, studies have demonstrated that high expression of TLR4/MyD88 is associated with liver metastases and is an independent predictor for poor prognosis, both in colitis-associated and in sporadic CRC cases." (PMID 29883450, 2018). "In vivo, SIGN-R1-knockout mice have been shown to have a significantly reduced susceptibility to LPS-induced shock, and SIGN-R1/TLR4-knockout mice displayed a reduced susceptibility to experimental colitis relative to the severity of the disease observed in wild-type or TLR4-knockout mice." (PMID 28607410, 2017). "We hypothesized that TLR4 expression is upregulated in colitis associated tumors and plays a pivotal role to induce iNOS and TNF-α expression through NF-κB pathway." (PMID 28408791, 2017). "For example, in the setting of chemically induced colitis TLR4 deficient mice were protected from colon carcinogenesis, while villin-TLR4 mice overexpressing TLR4 in the intestinal epithelium were highly susceptible to cancer when treated with dextran sodium sulphate and azoxymethane." (PMID 28531216, 2017). "Finally, we evaluated the level of IL-1β and TNF-α in colon tissues, and found a significant decrease of IL-1β and TNF-α in TLR4 deficient mice compared to control 7 days after the initiation of colitis." (PMID 27105524, 2016). "Interestingly, WT mice cohoused with villin-TLR4 mice displayed greater susceptibility to acute colitis than singly housed WT mice did." (PMID 26755160, 2016). "In conclusion, using our KO animals we have demonstrated that lack of endogenous AM causes an evident dysbiosis and an elevated TLR4 expression which might lead to a worse prognosis during colitis episodes." (PMID 27965594, 2016). "For Cd14, which is involved in the detection of lipopolysaccharides by TLR4, it was later demonstrated that a higher expression by gut epithelial cells is responsible for a lower colitis susceptibility in IL-10-/- mice with a C3H than with a C57BL/6 background." (PMID 23951309, 2013). "The expression of LPS specific Toll-like receptor 4 (TLR-4) in human colorectal cancer cells highlighted a key function of TLR system in the development of colitis-associated tumors, suggesting a role of this receptor in colorectal cancer development and progression." (PMID 24459329, 2013). "However other studies showed that, compared to wild-type mice, intestinal epithelial damage caused by colitis was milder in TLR4-deficient mice." (PMID 23082119, 2012). "Based on these findings, DSS or TNBS may cause colitis by lipid peroxidation and enterobacterial proliferation, which may deteriorate the colitis by regulating proinflammatory cytokines via TLR-4-linked NF-κB activation pathway." (PMID 20181058, 2010). "Additionally, mutations within the TLR4 gene locus can also lead to a functional loss of TLR4 that worsens DSS-induced colitis in mice by disturbing the intestinal homeostasis and barrier function." (PMID 21188218, 2010). "However, DSS and TNBS caused colitis in C3H/HeJ mice, which is TLR-4-defective, as well as in C3H/HeN mice." (PMID 20181058, 2010).
colitis (continued). "Furthermore, a recent study reported that TLR4 activation seems to promote the development of colitis-associated cancer by enhancing Cox-2 expression and increasing epidermal growth factor receptor (EGFR) signalling." (PMID 20145615, 2010). "TLR4 signaling has also been identified to be important in the development of colorectal cancer in colitis, and the inhibition of TLR4 signaling may be useful in protecting against colitis and colitis-associated cancer." (PMID 38540957, 2024). "Furthermore, RA acts as a considerably potent antitumor candidate against colitis-associated colorectal cancer by inhibiting toll-like receptor-4 (TLR4) and myeloid differentiation factor 2 (MD-2) complex-mediated nuclear factor-kappa B (NF-κB) and STAT3 activation." (PMID 39684626, 2024). "Inhibition of TLR4 significantly attenuates the proliferation of inflammatory tumour cells, a phenomenon that has been demonstrated in several studies, such as the inhibition of the expression of this gene impedes the growth of colitis-associated colon and ovarian cancer cells." (PMID 36936437, 2023). "After colitis induction in both mice strains, damage-associated molecular markers were released by the damaged colon tissue bound with the Toll-Like Receptors (mainly Tlr2 and Tlr4) and activated flares of inflammatory responses first-line defense mechanism of hosts." (PMID 35263357, 2022). "To investigate whether the gut microbiota in TLR4−/− mice was responsible for the enhanced susceptibility to colitis, we performed FMT experiments in which pseudosterile WT or TLR4−/− recipient mice were reconstructed with the microbiome from WT or TLR4−/− donor mice." (PMID 35761415, 2022). "Moreover, overexpression of TLR4 may induce the formation of cellular microenvironment supporting tumor growth and accelerate colitis-associated tumorigenesis." (PMID 36619207, 2022). "Similarly, our study proved that blocking MD2 not only markedly decreased colon cancer cell metastasis to lungs, but also inhibited the growth of colitis-associated colon cancer, via blocking the TLR4/MD2 complex formation and inhibiting the following pro-inflammatory NF-κB activation." (PMID 32210720, 2020). "BC may has the potential to modulate the immunological response as well as the severity of the intestinal inflammatory reaction modulating TLR4 and cytokine expression, reducing BW loss and histological score, balancing the microbiota, and finally decreasing the clinical signs of colitis in mice." (PMID 30138385, 2018). "Thus, we hypothesized that intestinal epithelium-specific constitutive TLR4 signaling would affect microbial composition, epithelial function, and colitis susceptibility." (PMID 26755160, 2016). "Thus, we questioned whether the altered microbiota of villin-TLR4 mice might play a role in the increased susceptibility of villin-TLR4 mice to colitis." (PMID 26755160, 2016). "Paeoniflorin has been shown to alleviate dextran sulfate sodium‐induced colitis through a TLR4‐dependent mechanism, demonstrating its anti‐inflammatory properties." (PMID 41561638, 2026). "paracasei 63 significantly alleviated colitis and improved intestinal barrier function, accompanied by reduced TLR4 expression, decreased NF-κB p65 phosphorylation, and decreased MLCK-related markers." (PMID 42279719, 2026). "Studies have reported that berberine can inhibit the TLR4/MyD88/NF-κB signaling pathway, thereby ameliorating colonic inflammatory responses and intestinal epithelial barrier dysfunction in colitis mice." (PMID 39810933, 2025). "Its anti-inflammatory effect is achieved by inhibiting the activation of the colitis-related TLR4/NF-κB signaling pathway." (PMID 40862149, 2025). "The study found that CW notably reduced the mRNA levels of pro‐inflammatory markers including TNF‐α, IL‐1β, IL‐6, Toll‐like receptor 4 (TLR4), and iNOS, while it enhanced the expression of the anti‐inflammatory cytokine IL‐10 in colitis." (PMID 39830908, 2025).
colitis (continued). "These coordinated reductions in both gene and protein expression of key inflammatory mediators substantiate ACP dose-dependent capacity to inhibit TLR4/NF-κB signaling, thereby mitigating systemic inflammation along the gut–liver axis in colitis." (PMID 40725052, 2025). "Administering pinocembrin, a bioactive component found in propolis, demonstrated effectiveness against colitis by inhibiting the aberrant activation of toll-like receptor 4 (TLR4)/nuclear factor-kappa B (NF-κB) signaling in mice." (PMID 40333577, 2025). "Casein, α‐lactalbumin, and L‐isoleucine have been demonstrated to alleviate DSS‐induced colitis by suppressing the TLR4/MyD88/NF‐κB signaling pathway." (PMID 40994452, 2025). "Sanhuang xiexin decoction (SXD) was able to modulate the gut-liver axis immunomodulation to ameliorate DSS-induced colitis secondary to hepatic injury, and attenuate hepatic inflammation and cholestasis by improving TLR4-NF-κB and bile acid metabolic pathways." (PMID 40066456, 2025). "TLR4 expression levels were also increased in both colitis and TA-administered colitis mice compared to the normal control group (p < 0.001)." (PMID 40333150, 2025). "Yet, in a murine model for colitis, 3′SL supplementation promoted dendritic cell function in a TLR4-dependent manner." (PMID 41404114, 2025). "In the context of colitis, an inflammation of the colon, Lp. plantarum Q7 EVs downregulated TLR4 and MyD88 expression, eventually leading to NFkB-mediated anti-inflammatory effects." (PMID 40948864, 2025). "Deposition of S. japonicum eggs protected mice against trinitrobenzenesulfonic acid (TNBS)-induced colitis via immunoregulatory mechanisms involving Th1/Th2 balance and TLR-4." (PMID 41024754, 2025). "Colon TLR-4 levels were 1.31 ± 0.20 pg/mg in the control group and significantly elevated to 3.55 ± 0.25 pg/mg in the colitis + saline group (*** p < 0.001; p = 0.0001), reflecting a marked activation of innate immune signaling." (PMID 40572721, 2025). "The EVs of Lc. rhamnosus GG also modulate the immune system and the composition of the microbiota via the TLR4-MyD88 axis, altering the metabolism of the entire microbiome towards an anti-inflammatory environment, thus protecting against colitis in mice." (PMID 40948864, 2025). "In a DSS‐induced colitis model, HZ dose‐dependently reduced the upregulation of TLR4 and NF‐κB, alleviating inflammation." (PMID 41164267, 2025). "Several components of A. muciniphila have been shown to interact with TLRs, particularly TLR2 and TLR4, and subsequently contribute to the amelioration of inflammation in colitis mice." (PMID 41488633, 2025). "TLR2 and TLR4 expressions were significantly higher in colitis mice compared to those in TA-administered normal mice." (PMID 40333150, 2025). "For example, EVs from L. plantarum Q7 reduced pro-inflammatory cytokines in the colon and serum of DSS-induced colitis mice, potentially through modulating the TLR4/MyD88/NF-κB pathway." (PMID 41301527, 2025). "Critically, existing studies focus on immune cell modulation which revealed its ability to suppress Toll-like receptor 4 (TLR4)/NF-κB signaling in macrophage-mediated colitis models." (PMID 40427406, 2025). "In the DSS colitis model, TLR4/MyD88 signaling consistently activates the IKK-NF-κB axis, thereby driving TNFα expression, potentially bypassing any inhibitory effects exerted by Bcl6." (PMID 40416976, 2025). "For example, it promotes tumorigenesis in colitis-associated colorectal cancer via the ERK1/2 pathway, and in collagen-induced arthritis, inhibition of the HMGB1/TLR4/STAT3 axis in M1 macrophages alleviates disease severity." (PMID 41009742, 2025). "The TLR4/NFκB pathway also plays a crucial role in colitis pathogenesis and interacts with the HMGB1/RAGE axis to further amplify the inflammatory response." (PMID 40606616, 2025). "In this study, increased mRNA expressions of TLR2 and TLR4 were observed in the DSS colitis group compared to those in the normal group." (PMID 40333150, 2025).
colitis (continued). "miRNA let-7b was found to ameliorate the severity of colitis via modulating Toll-Like Receptor 4 (TLR4) expression in IECs in response to adherent-invasive E. coli infection." (PMID 40004537, 2025). "Consistent with this, after infection with type B2 Escherichia coli, mice exhibit TLR4/MyD88/NF-κB activation and typical clinical symptoms and pathological changes of colitis." (PMID 40076603, 2025). "Mechanistically, ALG-RSV-CSNPs effectively attenuated colitis by significantly inhibiting the HMGB1-triggered RAGE/TLR4-NFκB inflammatory signaling pathway." (PMID 40606616, 2025). "HMGB1-activated RAGE/TLR4-NFκB signaling is a key regulator of inflammatory responses in DSS-induced colitis." (PMID 40606616, 2025). "The activation of the TLR4/MyD88/NF-κB signaling cascade—triggered by conditions such as colitis or LPS binding to TLR4—promotes the release of pro-inflammatory cytokines, thereby amplifying the inflammatory response." (PMID 41300540, 2025). "Baicalein has been shown to attenuate TNBS-induced colitis by inhibiting the TLR4/MyD88 signaling cascade and inactivating the NLRP3 inflammasome." (PMID 40130239, 2025). "The authors documented that PCSK9 inhibition suppressed the activation of TLR4/NF-κB in a rat model of colitis." (PMID 39982361, 2025). "In conclusion, probiotic VSL#3 is anticipated to be a first-choice medication in managing colitis because it reduces the production of NF-κB and TNF-α in rats with colitis via the TLR4-NF-κB signal pathway." (PMID 39323474, 2024). "rTsgal also alleviated DSS-induced murine colitis by inhibiting the TLR-4 (TLR-2)/MyD88/NF-κB signaling pathway, reducing excessive inflammatory responses, improving inflammatory cell infiltration and tissue damage." (PMID 39456703, 2024). "Specifically, the levels of TNF-α, IL-1β, IL-6, IL-10, IL-2, and IL-12 SOD, CAT, GSH-Px, and MDA were modulated in rats with colitis, also inhibiting TLR4/NF-κB pathway activation." (PMID 39494333, 2024). "Taken together, these results highlight that the protective effect of ruscogenin on DSS-induced colitis was associated with the attenuation of NLRP3 inflammasome activation and caspase-1-dependent pyroptosis by inhibiting the TLR4/NF-κB pathway." (PMID 38790951, 2024). "In line with this, it has been shown that CV at a dose of 200 mg/kg induced antioxidant and anti-inflammatory effects, upregulating the Nrf2/HO1 pathway and downregulating the Toll-like receptors 4 (TLR4)/NF-kB cascade in a murine model of colitis." (PMID 38671931, 2024). "Recent findings have indicated that TAK‐242 dose‐dependently alleviated DSS‐induced colitis symptoms and colonic lesions by downregulating TLR4 and JAK2/STAT3 mRNA and protein expression and increasing JAK2/STAT3 phosphorylation." (PMID 38676295, 2024). "These actions contribute to down-regulating the Toll-like receptor 4 (TLR4)/NF-κB inflammatory signaling pathway, thus improving colitis symptoms." (PMID 39130633, 2024). "The TLR4/NF-κB signaling pathway plays a critical role in the progression of colitis in mice and can mediate biological processes such as immunity and inflammation." (PMID 38892524, 2024). "Synbindin, a classical membrane tethering factor, regulates TLR4 signaling and suppresses the proinflammatory activation of macrophages in response to the microbiota during colitis." (PMID 39712025, 2024). "Cinnamomum verum essential oil has been reported to decrease the expression of Toll-like receptor-4 (TLR-4) in a dextran sodium sulfate-induced model of colitis and has been suggested to be effective in treating inflammatory bowel disease (IBD)." (PMID 38521924, 2024). "The findings imply that L. casei prevents the onset of acute DSS-induced colitis and that this impact primarily depends on TLR-4 status." (PMID 39323474, 2024). "The TLR4/NF-κB signaling pathway has close correlation with the colitis severity, which has been well confirmed in the colitis pathogenesis induced by DSS." (PMID 38998101, 2024).
colitis (continued). "TLR4 signal can be activated by multiple inflammatory mediators, and it is also an important factors resulting in mucosal barrier injury in colitis." (PMID 38535999, 2024). "The results suggested that BG had anti-inflammatory and antioxidant effects, and that the LPS/TLR4/NF-κB pathway was important for the alleviation of colitis by BG." (PMID 38783703, 2024). "TLR4 plays a sexual role in mice colitis by promoting the colonization of Akk bacteria in the intestine and upregulating the RORγt+ Treg cell-mediated immunosuppressive response." (PMID 39611150, 2024). "Res was used to inhibit the TLR4 signal, it was found that inhibiting TLR4 signal antagonized M1-Exo, and improved mouse colitis." (PMID 38535999, 2024). "It mitigates colitis severity, inflammation, and tumor development by modulating TLR4-mediated NF-κB and STAT3 activation, suppressing tumor growth factors." (PMID 38930793, 2024). "Previous studies have discovered that MD2 can serve as the helper TLR4 protein to promote colitis progression." (PMID 38535999, 2024). "As previously reported, Zanthoxylum peel extract can inhibit the expression of TNF-α, IL-1β, and IL-12 by regulating TLR4 and TLR4-related pathways in experimental colitis induced by DSS in mice and LPS-induced inflammation in J774.1 cells." (PMID 39519671, 2024). "According to previously published research, the TLR4 and NF‐κB signaling pathways are crucial for the development of colitis." (PMID 39723032, 2024). "The genus Akkermansia has anti-inflammatory potential and interacts with TLR-4 to improve colitis through up-regulation of the RORγt+ Treg cell-mediated immune response." (PMID 39140035, 2024). "Epithelial TLR4 activation is associated with increased dual oxidase 2 and NADPH oxidase 1 in IBD and CRC, impacting mucosal microbiota and promoting colitis-associated tumors." (PMID 38930793, 2024). "A similar observation was made in a colitis study in rats, where melatonin reduced the up-regulation of TLR4, MyD88, and NF-κB induced by trinitrobenzenesulfonic acid." (PMID 38255808, 2024). "Another study showed that L. plantarum AR113 alleviated dextran sulfate sodium (DSS)–induced colitis in mice by downregulating the TLR4/MyD88/NF-κB pathway in the colon." (PMID 37639209, 2024). "In the present study, oyster peptides were similarly able to alleviate the symptoms of DSS-induced colitis by maintaining intestinal barrier integrity, modulating the gut microbiota, and inhibiting the TLR4/NF-κB signaling pathway." (PMID 38892524, 2024). "Tomisetron, a receptor antagonist primarily used for anti-emesis, has also been shown to inhibit the development of colorectal cancer by inhibiting inflammation in colitis and TLR4/MyD88 signaling." (PMID 38785969, 2024). "In conclusion, Raf exerts a protective effect in colitis by modulating the gut microbiota and TLR4-MyD88-NF-κB pathway." (PMID 38928791, 2024). "For example, HA has been shown to protect against DSS-induced colitis by activating TLR4 and promoting the production of PGE2 (prostaglandin E2)." (PMID 39056761, 2024). "Since IL-4Rα signaling was required for the repair of DSS-induced colitis, we next sought to determine if the worsened colitis of DSS-treated TLR4-SNP mice was attributable to a decreased capacity for differentiation of M2a Mφ." (PMID 37768050, 2023). "It has been observed that L. plantarum AR113 alleviates DSS-induced colitis by modulating the TLR4-MyD88-NF-κB pathway and gut microbiota composition." (PMID 37764783, 2023). "The proofs revealed that kaempferol exerted an immunoregulatory effect in colitis murines through regulating the enteric flora and various metabolites, thus inhibiting the LPS-induced TLR4-NF-κB signal pathway." (PMID 36937890, 2023). "TLR4-SNP mice developed more severe colitis than WT mice throughout the experimental period as measured by “colonic symptom score”." (PMID 37768050, 2023).